CEP43 (centrosomal protein 43)
Description:
Required for anchoring microtubules to the centrosomes. Required for ciliation.
Synonyms: FGFR1OP; FOP
Tractability: PROTAC: ubiquitination databases record sites on it.
Gene: Protein-coding gene on chromosome 6 (166,999,174 to 167,052,718, forward strand). Ensembl gene ENSG00000213066.
Subcellular location: Cytoplasm, cytoskeleton, microtubule organizing center, centrosome; Cytoplasm, cytoskeleton, microtubule organizing center, centrosome, centriole; Cytoplasm, cytoskeleton, cilium basal body
Subcellular location (Human Protein Atlas): Basal body; Centrosome; Centriolar satellite
Pathways (Reactome):
Cell Cycle: AURKA Activation by TPX2; Loss of Nlp from mitotic centrosomes; Loss of proteins required for interphase microtubule organization from the centrosome; Recruitment of NuMA to mitotic centrosomes; Recruitment of mitotic centrosome proteins and complexes; Regulation of PLK1 Activity at G2/M Transition
Disease: Signaling by FGFR1 in disease; Signaling by cytosolic FGFR1 fusion mutants
Organelle biogenesis and maintenance: Anchoring of the basal body to the plasma membrane
Gene Ontology:
Molecular function: protein binding; protein homodimerization activity; protein kinase binding; protein tyrosine kinase inhibitor activity
Biological process: negative regulation of protein kinase activity; positive regulation of cell growth; positive regulation of cell migration; positive regulation of cell population proliferation; microtubule anchoring
Cellular component: centriole; centrosome; ciliary basal body; nucleus; perinuclear region of cytoplasm; cytosol; microtubule cytoskeleton; microtubule organizing center
Genetic constraint (gnomAD): Loss-of-function variants: 12 observed, 16.71 expected, observed/expected ratio (o/e) 0.72, 90% interval 0.46 to 1.16. The upper end of that interval is the gene's LOEUF score, 1.16, which puts it in group 5 of 6, group 1 being the genes least tolerant of losing a copy. Missense variants: 261 observed, 231.86 expected, observed/expected ratio (o/e) 1.13, 90% interval 1.02 to 1.25. Synonymous variants: 111 observed, 95.03 expected, observed/expected ratio (o/e) 1.17, 90% interval 1 to 1.37.
Homologues: Orthologues: macaque CEP43 (98% identical), chimpanzee CEP43 (95% identical), dog CEP43 (91% identical), guinea pig CEP43 (88% identical), rat Cep43 (87% identical), pig CEP43 (86% identical), mouse Cep43 (85% identical), rabbit CEP43 (74% identical), tropical clawed frog cep43 (50% identical), zebrafish cep43 (47% identical).
Diseases named in the same sentence as CEP43 in open-access papers:
CEP43 is named in the same sentence as 27 diseases in open-access papers, as found by Europe PMC text mining. Sharing a sentence is not in itself a finding about the gene and the disease. The quoted sentences say what the papers report.
lung carcinoma (4 papers, 2017 to 2025). "The first was an ncRNA intronic variant (rs12212247) in the polymorphisms of the centrosomal gene, CEP43 (also linked to numerous other traits, including lung cancer and stem cell myeloproliferative disorder)." (PMID 41425598, 2025).
chronic myelomonocytic leukemia (2 papers, 2020 to 2024). A myelodysplastic/myeloproliferative neoplasm which is characterized by persistent monocytosis, absence of a Philadelphia chromosome and BCR/ABL fusion gene, fewer than 20 percent blasts in the bone marrow and blood, myelodysplasia, and absence of PDGFRA or PDGFRB rearrangement. "For example, ZMYM2::FGFR1 most commonly presents as a T-lymphoblastic leukemia/lymphoma, BCR::FGFR1 and TPR::FGFR1 present histologically similar to chronic myeloid leukemia (CML), and CEP43::FGFR1 and CNTRL::FGFR1 show features similar to chronic myelomonocytic leukemia (CMML)." (PMID 38611061, 2024).
autoimmune hypothyroidism (1 paper, 2024). "A common genetic etiology was proposed between hypothyroidism and OLP81 and our study supports this, indicating variation at nine loci (IFIH1, LPP, CEP43, TNRC18, C12orf42, TNFSF11, ST3GAL6, IL2RA, and IKZF3) that are strongly associated with both LP and autoimmune hypothyroidism." (PMID 38776927, 2024). "Five of the most significant hits after HLA—TNFSF11, CEP43, LPP, C12orf42, and IFIH1—and ten overall coincide with the same direction of effect as seen in the FinnGen and/or UKBB autoimmune hypothyroidism GWAS." (PMID 38776927, 2024).
ciliopathies (1 paper, 2026). "By leveraging this phenotype-specific approach, we prioritized candidate genes for specific ciliopathies and identified likely pathogenic variants in CEP43, a previously unrecognized ciliopathy gene, in three previously unsolved cases." (PMID 41715205, 2026).
prostate carcinoma (1 paper, 2022). A carcinoma that arises from epithelial cells of the prostate gland. "The other genes showing molecular alterations in prostate cancer samples from highest to lowest are as follows; FGF2 (94/4990; 1.9%), NFIB (86/4990; 1.7%), CEP43 (62/4990; 1.2%), GSK3B (99/8961; 1.1%), DICER1 (101/8961; 1.1%), NR3C1 (53/4990; 1.1%) and ABHD2 (28/4,990; 0.6%)." (PMID 36468011, 2022).
CEP43 also shares sentences with these, for which no sentence is quoted: myeloproliferative disorder (4 papers); cancer (3); tumor (3); breast carcinoma (2); rheumatoid arthritis (2); vitiligo (2); acute myeloid leukemia (1); anemia (1); anxiety disorder (1); colorectal adenocarcinoma (1); colorectal cancer (1); epilepsy (1); hypothyroidism (1); insomnia (1); liver cancer (1); lymphoma (1); melanoma (1); myelodysplastic syndrome (1); preeclampsia (1); superficial spreading melanoma (1); uterine corpus endometrial carcinoma (1); Vogt-Koyanagi-Harada Syndrome (1).